ACE (angiotensin I converting enzyme)
Diseases named in the same sentence as ACE in open-access papers (continued):
Sharing a sentence is not in itself a finding about the gene and the disease.
glioblastoma (7 papers, 2004 to 2024). The most malignant astrocytic tumor (WHO grade IV). "When compared to LGG cases, ATP6AP2, AGTR1, and ACE were significantly higher in expression in glioblastomas, with AGTR1 showing the highest change in expression (5.7-fold higher)." (PMID 38607073, 2024). "The level of expression of ATP6AP2, AGTR1, AGTR2, and ACE genes in glioblastomas was similar to that observed in a range of other solid tumours and haematological cancers." (PMID 38607073, 2024). "The majority of RAS genes (ATP6AP2, AGTR1, AGTR2, and ACE) in our study were highly expressed in glioblastomas compared to LGGs." (PMID 38607073, 2024). "None of the synthesized peptidomimetics were able to completely inhibit infection of authentic SARS-CoV-2 (strains 20A.EU2 and Delta) in human glioblastoma U87.ACE+ cells or in human lung epithelial A549.ACE2.TMPRSS2+ cells up to 50 μM concentrations." (PMID 37240111, 2023). "We discuss their findings further below, offering the interpretation that glioblastoma overexpressed ACE functions to enhance peritumoral edema." (PMID 25211298, 2014). "High ACE mRNA expression was found in tumour vessels, confirming our previous observation of a high expression of ACE protein in glioblastoma vasculature by immunohistochemistry, but only at a very low level in the vessels of nontumoral tissue." (PMID 14997208, 2004). "To address the functions of the RAS in human glioblastoma, we first evaluated the effect of inhibiting renin and ACE in glioblastoma cells." (PMID 14997208, 2004). "The combination of TMZ + RT resulted in a slight but significant increase in the expression of ATP6AP2, AGTR1, and ACE, while AGT and the lowly expressed AGTR2 and REN remained unchanged across all 12 glioblastoma cell lines." (PMID 38607073, 2024). "ATP6AP2, AGTR1, AGTR2, AGT, and ACE had low frequencies of CNAs (<1%) in glioblastomas; however, REN was altered in 6% of glioblastoma cases." (PMID 38607073, 2024). "In cases of glioblastoma within the TCGA, ATP6AP2, AGTR1, ACE, and AGT had consistent expressions across samples, while AGTR2 and REN were lowly expressed." (PMID 38607073, 2024). "Progression-free survival (PFS) and overall survival (OS) were compared across TCGA glioblastoma cases, stratified from high and low expression of ATP6AP2, AGTR1, AGTR2, ACE, AGT, and REN genes." (PMID 38607073, 2024). "The baseline mRNA expression of RAS genes (ATP6AP2, AGTR1, AGTR2, AGT, ACE, and REN) were explored in 12 patient-derived glioblastoma cell lines." (PMID 38607073, 2024). "We studied the expression of RAS-related genes (ATP6AP2, AGTR1, AGTR2, ACE, AGT, and REN) in The Cancer Genome Atlas (TCGA) glioblastoma cohort, their relationship to patient survival, and association with tumour microenvironment pathways." (PMID 38607073, 2024). "The majority of genes (ATP6AP2, AGTR1, ACE, and AGT) were consistently expressed in glioblastoma cases, with the exception of AGTR2 and REN." (PMID 38607073, 2024). "Here, we investigated the gene expression of RAS components (ATP6AP2, AGTR1, AGTR2, ACE, AGT, and REN) in glioblastoma patient samples from The Cancer Genome Atlas (TCGA) and their association with survival outcomes and the expression of TME pathways." (PMID 38607073, 2024). "Baseline expressions of RAS genes were relatively similar to the TCGA glioblastoma cohort, where REN and AGTR2 were very lowly expressed while ATP6AP2, AGTR1, ACE, and AGT were consistently expressed." (PMID 38607073, 2024). "The expression of angiotensinogen, (pro)renin, ACE, and AT1 and AT2 receptors has been demonstrated in glioblastoma tumours and glioblastoma cells in culture, in which renin has a direct role in proliferation and/or survival." (PMID 16755291, 2006). "In the present study, we demonstrate that AGT, prorenin, ACE, AT1 and AT2 are synthesised and expressed in human glioblastoma and glioblastoma cells in culture, however at different levels of expression between the specimens." (PMID 14997208, 2004).
glioblastoma (continued). "The principle of our use of captopril in glioblastoma was active in a study of renal cell carcinoma (RCC), where immunohistochemical evidence for ACE expression on RCC, was first demonstrated in 1983 and this ACE activity was inhibited by captopril." (PMID 25211298, 2014). "We have previously shown that human glioblastoma cell lines did not express ACE activity, but that ACE is highly expressed in the abnormal vessels of human glioblastoma." (PMID 14997208, 2004). "We have previously shown high expression of ACE protein in human glioblastoma vessels; however, inhibition of ACE did not modify the growth of an experimental glioblastoma implanted in rat brains." (PMID 14997208, 2004). "We have also previously shown that ACE activity is not measurable in glioblastoma cells in culture." (PMID 14997208, 2004). "The majority of glioblastoma cases expressed ATP6AP2, AGTR1, ACE, and AGT but not AGTR2 and REN." (PMID 38607073, 2024).
hyperhomocysteinemia (7 papers, 2004 to 2025). A serious metabolic condition caused by mutations in the MTHFR gene, medications, or nutritional deficiency. "In the presented patient, the presence of the ACE I/D DD genotype likely exacerbated the effects of the PAI-1 4G/5G polymorphism and hyperhomocysteinemia by promoting a proinflammatory, prothrombotic, and antifibrinolytic vascular environment." (PMID 40981125, 2025).
hypertensive heart disease (7 papers, 2015 to 2025). Abnormal enlargement of the heart resulting from long-standing hypertension. "Amongst the different antihypertensives, ACE inhibitors and ARBs are considered first line drugs for therapy in hypertensive heart diseases." (PMID 35261921, 2021). "In line, the ACE inhibitor lisinopril or the ARB losartan were associated with reducing the extent of reactive fibrosis together with LV stiffness, and improving LV diastolic dysfunction, when given to small cohorts of patients with hypertensive heart disease." (PMID 35600469, 2022).
hypertensive nephropathy (7 papers, 2014 to 2025). Kidney damage that results from chronically elevated blood pressure; complications include glomerular damage resulting in proteinuria and hematuria. "Current treatments for hypertensive nephropathy encompass the use of calcium channel blockers, angiotensin-converting enzyme (ACE) inhibitors, and angiotensin receptor blockers." (PMID 40284165, 2025). "In addition to angiotensin-converting enzyme (ACE) dependent AngII generating system, chymase as an alternative AngII generating enzyme, was involved in the development of diabetic/hypertensive nephropathy." (PMID 25954204, 2015). "This was followed by another prospective interventional study of 59 patients with a clinical diagnosis of hypertensive nephropathy, all treated with regimens including an angiotensin-converting enzyme (ACE) inhibitor, who had an eGFR 20–59 mL/min/1.73 m2 and a serum bicarbonate <22 mEq/L." (PMID 24708763, 2014). "Also, miRNAs could serve as modifiable treatment markers as ACE inhibitors or as a β-blocker treatment of hypertensive nephropathy patients with reduced miR-103a-3p and albumin-to-creatinine ratio." (PMID 38804362, 2024). "The genotypes of ACE I/D (DD/II, adjusted OR, 2.21; 95% CI, 1.01–4.83) and G2350A (GA/GG, adjusted OR, 1.93; 95% CI, 1.02–3.63; AA/GG, and adjusted OR, 2.41; 95% CI, 1.11–5.22) were also significantly different for patients with hypertensive nephropathy compared with controls." (PMID 24977181, 2014). "In a second study by the same group, 120 patients with hypertensive nephropathy and CKD stage 2, all taking ACE inhibitors, were randomized in a blinded fashion to receive 0.5 mEq/kg/day sodium bicarbonate, sodium chloride, or matching placebo." (PMID 24708763, 2014). "Although antihypertensive treatments with ACE inhibitors, such as angiotensin receptor blockers, renin inhibitors, and aldosterone antagonists, could reduce the severity of hypertensive kidney disease, they are not enough to prevent the progression of hypertensive nephropathy." (PMID 33921823, 2021).
hyperthyroidism (7 papers, 2014 to 2025). Overactivity of the thyroid gland resulting in overproduction of thyroid hormone and increased metabolic rate. "ACE plasma levels are generally stable in individual adults, but blood ACE activities are significantly elevated in hyperthyroidism patients." (PMID 36979933, 2023).
hypothyroidism (7 papers, 2017 to 2025). Abnormally low levels of thyroid hormone. "Hypothyroidism in chicken embryos resulted in solid lung tissue on 19 days of incubation, a decrease in ventilation frequency, increase in thyroid receptor-β (TR), and attenuation of the natural increase in angiotensin converting enzyme (ACE) activity." (PMID 36523554, 2022). "Regarding to the existence of systemic diseases, two patients were hypertensive patients treated with angiotensin-converting-enzyme inhibitors (ACE inhibitors), one patient suffered hypothyroidism treated by hormone replacement therapy and two patients were taking gastric protector." (PMID 28358901, 2017). "Fetal hypothyroidism was found to have temporal and tissue‐specific effects on the expression of many RAS genes including AGT, ACE, ACE2, AGTR1, and AGTR2." (PMID 40939099, 2025).
Marfan syndrome (7 papers, 2010 to 2024). A disorder of the connective tissue. "Extrapolating from patients with aortopathy in Marfan syndrome there is also a suggestion that ACE inhibitors may have a role to play; however the evidence in BAV is still lacking." (PMID 22685681, 2012). "In addition, several animal studies have shown ACE medications to have beneficial effects against AAAs compared to one non-randomized study that found that an ACE inhibitor inhibited TAA growth in patients with Marfan syndrome." (PMID 36985395, 2023). "Research into patients with genetic aortopathies, like Marfan syndrome, has influenced the medical management of BAV aortopathy with beta-blockers or angiotensin-converting enzyme (ACE) inhibitors." (PMID 39452287, 2024). "Of the 27 patients with Marfan syndrome, 13 underwent aortic root surgery (ARS), 14 (9 ARS) are taking beta blockers and 10 (6 ARS) are treated with ACE inhibitors, CCB or ARB." (PMID 27151044, 2016). "While ARBs such as losartan and ACE inhibitors such as enalapril are teratogenic and hence not appropriate for use in pregnancy, hydralazine is well tolerated, making it an appealing alternative therapeutic strategy for Marfan syndrome, particularly in pregnant women." (PMID 26506064, 2015).
mastocytosis (7 papers, 2014 to 2023). A clonal myeloproliferative neoplasm characterized by the proliferation and accumulation of neoplastic mast cells in one or multiple organs or organ systems. "Several factors, such as the insect type, concomitant cardiovascular and respiratory disease, age, mastocytosis, high levels of serum tryptase, and previous use of angiotensin-converting enzyme (ACE) inhibitors, determine the severity of the clinical symptoms." (PMID 26184309, 2015). "Risk factors for a severe systemic anaphylactic reaction (SAR) after a Hymenoptera field sting include a preceding less severe sting reaction, a wasp sting, an increased baseline serum tryptase concentration (BSTC), mastocytosis, older age, ACE inhibitor medication, and male gender." (PMID 30402602, 2017).
nephritis (7 papers, 2011 to 2025). Inflammation of renal tissue. "High-dose corticosteroids (2 mg/kg/day), ACE inhibitors, and loop diuretics were initiated, based on a potential immune-related hepatitis, myositis, nephritis and TMA." (PMID 41158850, 2025). "Additionally, the thickening of the kidney glomerular basement membrane was suppressed, suggesting that ACE attenuated the progression of nephritis in SLE-prone mice." (PMID 18955361, 2011).
pulmonary embolism (7 papers, 2015 to 2023). The obstruction of the pulmonary artery or one of its branches by an embolus, sometimes associated with infarction of the lung. "Individuals with a D/D genotype were shown to have a higher incidence of pulmonary embolism and increased mortality rates, possibly due to increased levels of serum ACE." (PMID 35885894, 2022). "Currently, no study has investigated ACE I/D polymorphism involvement in COVID-19 disease complicated by pulmonary embolism, hence the aim of the present pilot study." (PMID 33585520, 2020).
renal tubular dysgenesis (7 papers, 2010 to 2025). "The etiology of renal tubular dysgenesis (RTD) is linked to mutations in the angiotensin-converting enzyme (ACE)." (PMID 21695262, 2011). "Genetic loss of function of AGT (angiotensinogen), REN (renin), ACE (angiotensin-converting enzyme), or AGTR1 (type-1 angiotensin II receptor) leads to renal tubular dysgenesis (RTD)." (PMID 33768328, 2021). "Variants in ACE and AGT, associated with renal tubular dysgenesis, were classified as VUS (11.8%)." (PMID 41288877, 2025). "Complete absence of ACE in humans leads to renal tubular dysgenesis (RTD), a severe disorder of renal tubule development characterized by persistent fetal anuria and perinatal death." (PMID 20454656, 2010).
sickle cell disease (7 papers, 2011 to 2025). Sickle cell anemias are chronic hemolytic diseases that may induce three types of acute accidents: severe anemia, severe bacterial infections, and ischemic vasoocclusive accidents (VOA) caused by sickle-shaped red blood cells obstructing small blood vessels and capillaries. "Additionally, APOL1RRV patients suffering from CKD associated with sickle cell disease showed a more significant reduction in albuminuria when treated with ARBs or Angiotensin I Converting Enzyme (ACE) inhibitors." (PMID 40001508, 2025). "Several diseases have increased circulating and urinaryangiotensin-converting enzyme (ACE) activity, but there is littleinformation about changes in ACEs activity in children with sickle celldisease (SCD)." (PMID 33973994, 2021). "The sickle-cell disease (SCD) as the most frequent type of hemoglobinopathy is treated with analgesics, antibiotics, angiotensin converting enzyme (ACE) inhibitors and hydroxyurea." (PMID 31528501, 2019). "Also the use of angiotensin converting enzyme (ACE) inhibitors, which reduces glomerular hyperfiltration, has been reported to be effective in reducing proteinuria in sickle cell disease." (PMID 21533141, 2011).
silicosis (7 papers, 2012 to 2025). Silicosis is a respiratory disease caused by breathing in (inhaling) silica dust. "Angiotensin converting enzyme (ACE) was found sequent higher in healthy controls, exposed workers, simple silicosis and complicated silicosis in the largest and more recent studies on this topic." (PMID 40027509, 2025). "Considering the pulmonary function status, serum ACE level, was higher in those with abnormal pulmonary function and silicosis than those with abnormal pulmonary function and free from silicosis." (PMID 27275272, 2015). "It was found that 40% (12/30) of the silicosis group showed higher level of Cu and 80% (24/30) showed higher level of ACE than normal values." (PMID 27275272, 2015). "In silicosis and other dust-related lung fibrosis, both the endothelial cells and macrophages were considered to be the source of increased serum ACE levels." (PMID 27275272, 2015). "In the present study, we observed that AngII level in plasma and lung tissue was up-regulated by silicosis, and similarly that ACE and AT1 in the lung were also elevated." (PMID 22802960, 2012). "Increased serum ACE activities were reported in silicosis patients compared to control subjects, but this activity did not reflect the severity of the disease as determined by chest x-ray changes and respiratory function tests, did not give further information on the progression of the disease." (PMID 27275272, 2015). "It is likely that the serum ACE level in silicosis, at least partly, reflects the accumulation and the increased degradation of macrophages; this indicates that macrophages may be a source of serum ACE in silicosis." (PMID 27275272, 2015). "While 4.8% (2/42) of the non-silicosis group showed higher level of ACE than normal values." (PMID 27275272, 2015). "However, other studies confirmed an elevation in serum ACE activities in silicosis patients." (PMID 27275272, 2015). "This has been proven by the suppressive effect of angiotensin convertase 2 or captopril on the ACE/angiotensin II/AT1 axis, which reduced the epithelial-mesenchymal transition in experimental silicosis." (PMID 40027509, 2025). "Measurement of serum levels of Angiotensin converting enzyme (ACE), Copper (Cu) and Ceruloplasmin (Cp) in cement workers occupationally exposed to silica dust as biomarkers of exposure rather than biomarkers of effect for silicosis." (PMID 27275272, 2015).
Thromboembolism (7 papers, 2009 to 2025). The formation of a blood clot inside a blood vessel that subsequently travels through the blood stream from the site where it formed to another location in the body, generally leading to vascular occlusion at the distant site. "In fact, ACE D/D homozygosis has been associated to thromboembolism occurrence in subjects actually without predisposing factors and traditional thrombophilic alterations in other disease." (PMID 33585520, 2020).
urinary tract infection (7 papers, 2019 to 2026). "The highest cumulative incidence (12.3%) was found for the potential prescribing cascade of angiotensin‐converting enzyme (ACE) inhibitor potentially causing urinary tract infections treated with antibacterials." (PMID 41490470, 2026). "For eight patients, the pharmacist preferred to monitor the patient, including those on ACE inhibitors causing cough (treated with cough suppressants) and ACE inhibitors causing urinary tract infections (treated with antibiotics)." (PMID 39954224, 2025). "SOB: shortness of breath; EF: ejection fraction; UTI: urinary tract infection; ACE: angiotensin-converting enzyme." (PMID 34804663, 2021).
venous thromboembolism (7 papers, 2014 to 2025). Occlusion of the lumen of a vein by a thrombus that has migrated from a distal site via the blood stream. "Regarding the effects of the ACE I/D polymorphism on coagulation, numerous studies have investigated its association with venous thromboembolism." (PMID 40981125, 2025).
aortic regurgitation (6 papers, 2009 to 2025). "His severe aortic insufficiency and ventricular dilatation remained stable over the past 10 years under ACE inhibitor treatment." (PMID 40276563, 2025). "ACE inhibitors, ARBs, and diuretics were similarly used in patients with mitral and aortic regurgitation (P>0.05)." (PMID 37181974, 2023). "ACE inhibitors and ARBs are considered the cornerstone of the management of aortic regurgitation." (PMID 37181974, 2023). "ACE inhibitors or angiotensin receptor blockers (ARBs) are cornerstones of therapy in the management of aortic regurgitation as they decrease the afterload and decrease the mean aortic pressure, thereby decreasing the extent of regurgitation and total regurgitation volume." (PMID 37181974, 2023). "Each spectrum of severe valvular heart disease was lacking the cornerstone therapy such as beta-blockers in mitral stenosis and ACE inhibitors or angiotensin receptor blockers (ARBs) in mitral and aortic regurgitation along with recommended injectable benzathine penicillin prophylaxis." (PMID 37181974, 2023). "In addition, ACE inhibitor treatment is widely recommended in moderate to severe aortic regurgitation." (PMID 20062791, 2009). "Conservative therapy using ACE inhibitors, as used in conventional aortic regurgitation, may slow down the progression of valvular dysfunction." (PMID 20062791, 2009). "Most of the patients across each spectrum of rheumatic valvular heart disease were lacking the cornerstone therapy such as beta-blockers in mitral stenosis and angiotensin-converting enzyme (ACE) inhibitors or angiotensin receptor blockers (ARBs) in mitral and aortic regurgitation." (PMID 37181974, 2023).